HORMAD1 (HORMA domain containing 1)
Diseases named in the same sentence as HORMAD1 in open-access papers (continued):
Sharing a sentence is not in itself a finding about the gene and the disease.
cancer (continued). "Within any given tumor approximately 20–40% of individual cancer cells express either HORMAD1 or CT83, and around 5–20% express both." (PMID 38467851, 2024). "A GSEA analysis revealed that the “HORMAD1 + CT83” signature detected in HMLE cells was significantly correlated to the transcriptome profile of double-positive cancer cell lines and with the transcriptome of double-positive tumors." (PMID 38467851, 2024). "This is especially the case with HORMA domain-containing protein 1 (HORMAD1; CT46) expressing cancers." (PMID 37371097, 2023). "While in meiosis HORMAD1 regulates DNA double strand break repair during chromosomal crossover, and in cancer it influences genomic instability." (PMID 37371097, 2023). "Next, we aimed to investigate if HORMAD1 functions in DNA replication and/or the response to replication stress in cancer cells." (PMID 37838177, 2023). "Our results revealed notably elevated HORMAD1 transcription expression in all but four cancer tissues compared to their corresponding normal adjacent tissue samples." (PMID 37371097, 2023). "Two reports have suggested HORMAD1 promotes genomic instability when inappropriately expressed by biasing cancer cells toward using the error-prone DNA repair pathways translesion synthesis, nonhomologous end joining, or by blocking DNA mismatch repair." (PMID 37838177, 2023). "The multiple studies of HORMAD1 function in tumors suggest a mixture of genomic protection and disruption, depending on the stage and type of cancer or additional changes in DNA repair pathways (BRCA1/2 mutation, ATM/ATR loss, and so on)." (PMID 37838177, 2023). "The ectopic expression of HORMAD1 was documented by us and others across a variety of aggressive cancers." (PMID 37371097, 2023). "We analyzed HORMAD1 mRNA expression across 23 cancer subtypes using TCGA data paired with normal adjacent tissue samples." (PMID 37371097, 2023). "Our work highlights that HORMAD1 is an intriguing novel therapeutic target for the treatment of SCCs and other aggressive cancers." (PMID 37371097, 2023). "In this study, we demonstrated that elevated HORMAD1 attenuates detrimental genomic instability in SCCs, thereby promoting cancer cell survival." (PMID 37371097, 2023). "The bimodal pattern of HORMAD1 expression observed in TNBC was previously reported in different types of cancer, including BC." (PMID 36852691, 2023). "Ultimately, suppression of HORMAD1 in LUAD cancer cells leads to the accumulation of DNA damage and chromosomal aberrations, which is significantly amplified in the presence of replication stress." (PMID 37838177, 2023). "The cancer/testis antigen HORMAD1 is a mechanical regulator that modulates DNA homologous recombination repair and mismatch repair in multiple cancers." (PMID 35347116, 2022). "Emerging evidence has demonstrated that HORMAD1 can promote either chemoresistance or chemosensitivity by targeting the homologous recombination repair pathway in different types of cancer." (PMID 35347116, 2022). "Focal amplification peaks, including the well‐studied cancer‐driven gene MYC (8q.24.21) and several antiapoptotic genes (MCL1, HORMAD1, and ECM1 on 1q21.2), were identified in the high‐risk patients, along with a focal deletion peak at 13q14.2." (PMID 34894177, 2022). "The group of Yidan Liu showed that aberrant expression of HORMAD1 compromises DNA mismatch repair in cancer cells." (PMID 35251135, 2022). "Originally identified as a cancer/testis antigen, HORMAD1 is aberrantly expressed in several cancers." (PMID 32647118, 2020). "In this study, we report that aberrantly expressed HORMAD1 interacts with MCM8–MCM9 complex in cancer cells." (PMID 32647118, 2020). "To provide mechanistic insights into the function of HORMAD1 in cancer cells, we established 293T cells stably expressing S-Flag-streptavidin binding protein (SFB)-tagged HORMAD1 and performed tandem affinity purification and mass spectrometry analysis." (PMID 32647118, 2020).
cancer (continued). "Nevertheless, our findings indicate that the compromised DNA mismatch repair has the potential to be exploited for targeted therapy of HORMAD1-expressing cancers." (PMID 32647118, 2020). "In order to examine the expression of HORMAD1 in cancers thoroughly, we conducted pan-cancer analysis of HORMAD1 expression in 25 types of cancers using RNA sequencing data from The Cancer Genome Atlas (TCGA)." (PMID 32647118, 2020). "Taken together, HORMAD1 is widely expressed in group I and II cancers that include 18 cancer types and a large number of cancer samples." (PMID 32647118, 2020). "Collectively, these data strongly support that MCM8–MCM9 complex is a binding partner of HORMAD1 in cancer cells." (PMID 32647118, 2020). "Taken together, our study provides mechanistic insights into HORMAD1’s functions in cancer cells, which can potentially be exploited for targeted therapy of HORMAD1-expressing cancers." (PMID 32647118, 2020). "Together, consistent with most studies, these observations suggest that HORMAD1 promotes HR repair in cancer cells." (PMID 32647118, 2020). "In this study, we have shown that meiosis-specific protein HORMAD1 is widely expressed in many cancers." (PMID 32647118, 2020). "As a consequence, HORMAD1-expressing cancer cells have reduced MLH1 chromatin binding and DNA mismatch repair defects." (PMID 32647118, 2020). "Originally identified as a cancer/testis antigen, HORMAD1 is also aberrantly expressed in several cancers." (PMID 32647118, 2020). "The mechanism how HORMAD1 promotes HR repair in cancer cells requires further investigation in future." (PMID 32647118, 2020). "Since HORMAD1 is widely expressed in many cancers, such therapy will potentially benefit a large group of patients with HORMAD1-expressing cancers." (PMID 32647118, 2020). "Due to inconsistency between results obtained from different groups in previous studies, we performed an independent evaluation HORMAD1’s function in HR repair in cancer cell lines using a DR-GFP plasmid reporter." (PMID 32647118, 2020). "Collectively, these results reveal that HORMAD1 expression compromises DNA mismatch repair in cancer cells, and the effect of HORMAD1 expression is roughly half of MLH1 KO." (PMID 32647118, 2020). "Here, we show that HORMAD1 is aberrantly expressed in a wide variety of cancers and compromises DNA mismatch repair in cancer cells." (PMID 32647118, 2020). "In group I, HORMAD1 expression plot showed an approximately bimodal shape, suggesting that each type of cancer in this group contains two distinct populations: HORMAD1-positive and HORMAD1-negative cancers." (PMID 32647118, 2020). "Knockout of HORMAD1 in cancer cells resulted in increased sensitivity to IR treatment, and the HR-mediated repair pathway targeting IR-induced DSBs was attenuated in HORMAD1-knockout cancer cells." (PMID 32355263, 2020). "This neomorphic role of HORMAD1 in HR is analogous to the cancer cell specific role of another CT antigen, MAGE-A4 which also activates an S-phase-coupled DNA repair mechanism to confer DNA damage tolerance." (PMID 30333500, 2018). "On the other hand, investigation of the Genomics of Drug Sensitivity in Cancer dataset revealed significantly reduced sensitivity of HORMAD1-overexpressing BLBC cell lines to Rucaparib, a commonly used PARPi." (PMID 30046392, 2018). "We performed structure-function analyses to define mechanisms of HORMAD1 regulation by DSB signaling in cancer cells." (PMID 30333500, 2018). "In this report we investigate possible roles of CT antigens in genome maintenance in cancer cells and identify a new role for HORMAD1 in facilitating DNA repair." (PMID 30333500, 2018). "Many tumors aberrantly overexpress HORMAD1 yet the potential impact of this CT antigen on cancer biology is unclear." (PMID 30333500, 2018). "Interesting questions remain concerning the mechanisms of HORMAD1 expression in tumors, and the molecular basis for HORMAD1-induced HR in cancer cells." (PMID 30333500, 2018).
cancer (continued). "The Cancer/Testes (CT) Antigen HORMAD1 is germ cell-restricted and plays developmental roles in generation and processing of meiotic DNA Double Strand Breaks (DSB)." (PMID 30333500, 2018). "HORMAD1 mediates chromosomal recombination during meiosis and is overexpressed in several cancers including melanoma, inconsistent with its observed negative cSCC association." (PMID 30323283, 2018). "It will be interesting to identify subsets of different cancers that depend most on HORMAD1 for DNA damage tolerance (perhaps including tumors driven by co-amplified DDR2 oncogene)." (PMID 30333500, 2018). "The new role we define for HORMAD1 in promoting DSB repair in cancer cells differs from how Hormad1 impacts repair radiation-induced DSB in mouse meiotic cells." (PMID 30333500, 2018). "HORMAD1 is a testis germ cell protein that has been suggested to play roles in genomic instability in cancer." (PMID 30046392, 2018). "Therefore, we hypothesize that the HORMA domain of HORMAD1 mediates reversible binding to DNA repair proteins via a safety belt-based mechanism and/or that the C-terminal of HORMAD1 associates with another HORMA domain-containing protein to facilitate DNA repair in cancer cells." (PMID 30333500, 2018). "Hormad1, also referred to as cancer/testis 46, is involved in chromatin binding and highly expressed in testis and was identified as a tumor antigen." (PMID 25166861, 2014). "Although there is no data specifically implicating these pathways in cancer, it is important to note that SPO11, DMC1, and HORMAD1 have all been shown to be increased in cancer." (PMID 23840955, 2013). "HORMAD1's precise role and prognostic value in cancer patients is controversial." (PMID 36852691, 2023). "This suggests that the function of HORMAD1 in the treatment response may diverge in different cancers models and may depend on the type of chemotherapy." (PMID 36852691, 2023). "Cancers expressing high levels of HORMAD1 exhibit increased resistance to select treatments." (PMID 37371097, 2023). "How HORMAD1 and these genes are related remains unknown but may provide a rationale as to why high HORMAD1 expressing cancers exhibit advanced heterogeneity, increased resistance to therapy, and poor clinical prognosis." (PMID 37371097, 2023). "Since similar results were observed in epithelial cancer cell lines, the relationship between HORMAD1 and genomic instability may be relevant in other cancer types." (PMID 37371097, 2023). "However, many studies have shown that HORMAD1 is significantly upregulated in several cancers where it correlates with increased genomic instability and poor patient prognosis." (PMID 35251135, 2022). "HORMAD1 is a meiotic gene that becomes aberrantly expressed in cancers." (PMID 35768547, 2022). "By identifying bimodal and tumour cell specific somatic expression of the meiotic protein HORMAD1 as a potential patient selection biomarker our study contributes to a growing body of evidence that TLS dependency is a tractable therapeutic target in cancer." (PMID 35768547, 2022). "Consequently, HORMAD1-expressing cancer cells have reduced MLH1 chromatin binding and DNA mismatch repair defects." (PMID 35251135, 2022). "HORMAD1 might have opposing effects on HR in different cancers due to tissue-specific expression of HR pathway regulators targeted by HORMAD1." (PMID 35251135, 2022). "MCM8 and MCM9, which form a stable complex, were among the most abundant proteins identified, suggesting that HORMAD1 might have a functional link with MCM8–MCM9 complex in cancer cells." (PMID 32647118, 2020). "This indicates that HORMAD1 can shuttle between nucleus and cytosol in cancer cells." (PMID 32647118, 2020). "This is the first time that the function and mechanism of HORMAD1 in cancer cells are discovered." (PMID 32647118, 2020). "This possibility is consistent with our finding that HORMAD1 is widely expressed in many cancers." (PMID 32647118, 2020).
cancer (continued). "Many cancer cells aberrantly express the cancer/testes antigen HORMAD1." (PMID 32355263, 2020). "Analyses of the rest 24 cancer types revealed that HOMRAD1 high expression could be found in most cancer types, suggesting that HORMAD1 is widely expressed in cancers." (PMID 32647118, 2020). "To further interrogate the cellular studies, we investigated the mutation load status in human cancer samples with or without HORMAD1 expression in TCGA database." (PMID 32647118, 2020). "Studies have revealed that HORMAD1 can actively participate in cellular activities in cancers." (PMID 32647118, 2020). "Therefore, a small but non-negligible percentage of samples within each type of group II cancers has high expression of HORMAD1." (PMID 32647118, 2020). "It is postulated that this is mediated by HORMAD1 promoting efficient re‐sectioning of DSBs, making the repair of therapeutic‐induced damage more effective in cancer cells, a process that could potentially give these cells a greater evolutionary capacity." (PMID 31102330, 2019). "Therefore, putative effects of HORMAD1 on genome stability in cancer are likely to result from neomorphic activities unrelated to its HORMAD2 and CCDC36-mediated roles in germ cell development." (PMID 30333500, 2018). "Therefore, we used a pharmacological inhibitor (KU55933) to test the potential contribution of ATM signaling to HORMAD1 regulation in cancer cells." (PMID 30333500, 2018). "Targeted therapies against HORMAD1-mediated HR could sensitize cancer cells to intrinsic or radiation-induced DSB yet would be innocuous to normal somatic cells and devoid of side-effect toxicity." (PMID 30333500, 2018). "However, in our analysis of TCGA data we also noticed that HORMAD1 is often co-expressed with DDR2 (encoding a collagen-binding receptor tyrosine kinase), a known oncogenic driver in NSCLC and other cancers." (PMID 30333500, 2018). "In addition, we have chosen to apply HORMAD1 overexpression model instead of genetic inhibition, as the acute loss of HR repair genes such as BRCA1 have been shown to be toxic to cancer cells." (PMID 30046392, 2018). "Harnessing this knowledge may enable development of chemical probes and small molecule inhibitors that disrupt interactions between specific HORMAD1 and its effectors to enhance radiotherapy and kill cancer cells." (PMID 30333500, 2018). "However, HORMAD2 is not expressed in H1299 cells and therefore the IRIF activity of HORMAD1 in cancer cells is HORMAD2-independent." (PMID 30333500, 2018). "However, nothing is known regarding the regulation of HORMAD1 (or its putative functions) in cancer cells (in any species)." (PMID 30333500, 2018). "Pathological HORMAD1-dependent HR may represent an important enabling characteristic of cancer cells." (PMID 30333500, 2018). "The HORMAD2- and CCDC36-independence of DSB repair in our HR assays is consistent with the hypothesis that HORMAD1 acquires neomorphic DNA repair activities when mis-expressed in cancer cells." (PMID 30333500, 2018). "Given the role of HORMAD1 in disrupting normal cellular functions, our study suggests that HORMAD1 might not be passively expressed by global hypomethylation in cancers, but might be selected to facilitate cancer development." (PMID 32647118, 2020). "Examples include the HORMAD1/2, MND1, MEIOB and SYCP3 genes, which directly influence the HR activity of cancer cells." (PMID 35251135, 2022). "HORMAD1, also known as CTA46, is a member of the cancer/testis antigen (CTA) family, whose expression is restricted to germ cells but is aberrant in diverse cancers." (PMID 35347116, 2022). "As expected, ectopically co-expressed CCDC36 was co-immunoprecipitated with HORMAD1, indicating that CCDC36 and HORMAD1 can interact in cancer cells." (PMID 30333500, 2018). "To test this, we analyzed the sensitivity of HORMAD1-high and HORMAD1-low cell lines to PARP inhibitors using the Genomics of Drug Sensitivity in Cancer (GDSC) dataset." (PMID 30046392, 2018).
cancer (continued). "Consistently, we found histone marks associated with promoter activity (H3K27ac, H3K4me3) in sperm and in a basal-like cancer cell line positive for HORMAD1 and CT83 (MDA-MB-436) but not in the normal breast or negative breast cell lines." (PMID 38467851, 2024). "We subsequently asked whether the “HORMAD1 + CT83” signature, as seen in vitro, is germane to the transcriptional profile of cancer cell lines and basal tumors expressing both genes." (PMID 38467851, 2024). "Here we have identified HORMAD1 as a unique negative regulator of DNA mismatch repair machinery that is specifically expressed in cancers but not in normal somatic cells." (PMID 32647118, 2020). "Taken together, our work indicates that HORMAD1 acquires cancer cell-specific DSB repair functions that are independent of its roles in meiosis." (PMID 30333500, 2018). "It is possible that in an HR-sufficient cancer cell, HORMAD1 overexpression does not lead to further increases in (already high) HR capacity." (PMID 30333500, 2018). "Notably, HORMAD1 can regulate DNA double-strand break repair in cancer cells through either homologous recombination or non-homologous end-joining." (PMID 38596293, 2024). "In contrast, in triple negative breast cancer, HORMAD1 suppresses homologous recombination and induces non-homologues end joining repair, hence sensitizing cancer cells to the use of homologous recombination-targeting therapy such as platinum-based chemotherapy." (PMID 38596293, 2024). "The upstream regulation of HORMAD1 expression in cancer has not been investigated." (PMID 37371097, 2023). "Therefore, HORMAD1 expression compromises DNA mismatch repair by interfering chromatin binding of MLH1 in cancer cells, which is similar to cells without MCM8–MCM9 complex." (PMID 32647118, 2020). "However, the functions of HORMAD1 in cancer cells are still not clear." (PMID 32647118, 2020). "We have noticed that HORMAD1 depletion leads to reduced MSL1 levels and specifically decreases H4K16Ac levels (but not global Histone H4 acetylation in cancer cells (data not shown)." (PMID 30333500, 2018).